KEAP1 (kelch like ECH associated protein 1)
Diseases named in the same sentence as KEAP1 in open-access papers (continued):
Sharing a sentence is not in itself a finding about the gene and the disease.
acute liver failure (5 papers, 2018 to 2025). Rapid deterioration of liver function causing encephalopathy and coagulopathy. "A further example relates to miRNA-125b-5p which was reported to alleviate acute liver failure by regulating the Keap1/Nrf2/HO-1 pathway." (PMID 39424772, 2025). "Upregulation of miR-125b-5p can alleviate acute liver failure by regulating the Keap1/Nrf2/HO-1 pathway, and regulation of miR-125b-5p may serve as an alternative intervention for liver failure." (PMID 36268033, 2022). "Thus, the activation of Keap1/Nrf2/HO-1 signaling plays an essential role in inhibiting paracetamol-induced acute liver failure." (PMID 34199606, 2021). "The Nrf2/Keap1 pathway is a key cellular defense mechanism that plays a key role in the regulation of phase II detoxifying and antioxidant enzymes in preventing APAP-induced acute liver failure." (PMID 31214283, 2019).
alcoholic liver diseases (5 papers, 2022 to 2025). A disorder caused by damage to the liver parenchyma due to alcohol consumption. "Therefore, inhibiting Keap1 activity or disrupting Keap1/Nrf2 interaction was considered an effective approach to alleviating the oxidative stress caused by alcoholic liver damage." (PMID 40362898, 2025). "Previous research identified the Keap1/HO-1 signaling pathway as a key target for alleviating alcoholic liver damage." (PMID 40362898, 2025). "In conclusion, XZTZ demonstrates potential in alleviating alcohol-induced liver injury, oxidative stress, and inflammation possibly through modulation of Nrf2/Keap1 and MAPKs/NF-κB signaling pathways, suggesting its potential as a therapeutic option for patients with alcoholic liver disease." (PMID 38681193, 2024). "In animal models of alcoholic liver disease, HSYA regulates the STAT3/NF-κB signaling pathway, inhibits inflammatory cascade reactions, reduces lymphocyte infiltration and inflammatory damage, activates the Keap1/Nrf2 pathway, and reduces oxidative damage." (PMID 40584613, 2025).
Arthritis (5 papers, 2018 to 2023). Inflammation of a joint. "Resveratrol alleviated arthritis through the activation of Nrf2-ARE (antioxidant response elements) signaling pathway via SIRT1/NF-κB/miR-29a-3p/Keap1 and SIRT1/NF-κB/miR-23a-3p/cul3 signaling pathway." (PMID 33499333, 2021).
breast tumors (5 papers, 2020 to 2024). "We observed a different pattern in breast tumors that metastasize to lung and harbor a mutation in KEAP1, KRAS, STK11, or EGFR." (PMID 32374727, 2020). "Genetic mutations in NFE2L2 and KEAP1 are uncommon in human breast tumors." (PMID 38488001, 2024). "In addition, the expression level of TRIM25 and Nrf2 were also inversely correlated to Keap1 in breast tumor tissues from TCGA database." (PMID 31953436, 2020). "Breast tumors NPSH level may provide a localized reducing environment where active Keap1 may negatively regulate Nrf2 and hinders the SULT1E1 expression as in few patients." (PMID 32158360, 2020).
cataract (5 papers, 2017 to 2024). Partial or complete opacity of the crystalline lens of one or both eyes that decreases visual acuity and eventually results in blindness. "Recent studies have shown that, in patients with cataracts, ROS induced a reduction in DNA methylation in the Keap1 promoter gene, activating the expression of Keap1 protein." (PMID 36676026, 2022). "Because Keap1 methylation is accredited to inhibiting Nrf2 activation and is found in higher amounts of cataract patients, drugs increasing methylation or decreasing demethylation are being evaluated for their aptitude in restricting cataract pathology." (PMID 28473877, 2017). "This group has also attributed valproic acid, a common antiseizure drug, in stimulating the demethylation of Keap1 and increasing the incidence of cataracts in epilepsy patients." (PMID 28473877, 2017). "In rabbit models of keratoconus and cataract, SFN has been shown to protect corneal and lens epithelial cells from oxidative stress injury by activating the Keap1‐Nrf2‐ARE pathway and the Nrf‐2/HO‐1 antioxidant pathway." (PMID 39139965, 2024). "In conclusion, the Nrf2/Keap1/ARE signaling pathway is a promising preventive and therapeutic target against oxidative stress for cataracts." (PMID 28722304, 2017). "Although none of the single nucleotide polymorphisms for Nrf2 or Keap1 gene showed predilection for cataracts, one Nrf2 haplotype GAAAA did determine the advancement of cataract formation by showing a significant correlation of this haplotype with the onset of cataracts four years earlier." (PMID 28473877, 2017).
heart failure (5 papers, 2018 to 2024). Inability of the heart to pump blood at an adequate rate to meet tissue metabolic requirements. "In contrast, the protein expression of Kelch-like ECH-associated protein 1 (Keap-1), a negative regulator of Nrf2, was elevated after the occurrence of heart failure but reduced after ASI treatment." (PMID 33253607, 2020). "In summary, YHR may provide cardioprotective effects in heart failure through inhibiting the Keap1/Nrf2/HIF-1α apoptosis pathway." (PMID 33739243, 2021).
malaria (5 papers, 2016 to 2021). Malaria is a serious and sometimes fatal disease caused by a parasite that commonly infects a certain type of mosquito which feeds on humans. "To investigate whether malaria parasites employ a similar molecular mechanism, we aligned KEAP1 protein sequence from humans with PvK12 which revealed that these Cys residues are not conserved in Plasmodium, while 6–8 conserved Cys residues are present in the Kelch domain in the malaria parasite." (PMID 27821166, 2016).
mastitis (5 papers, 2023 to 2025). Inflammation of breast tissue during lactation or postpartum due to an obstructed duct or infection. "Collectively, these data implicated miR-223 as modulating the NLRP3 inflammasome and Keap1-medidated oxidative stress pathway in experimental mastitis." (PMID 37710276, 2023). "Collectively this review article aims to explore the potential of bioactive compounds in mitigating mastitis by targeting the Nrf2/KEAP1 signaling pathway." (PMID 39991157, 2025). "Here, we summarize recent studies to highlight the therapeutic potential of Nrf2/KEAP1 pathway in the prevention and treatment of mastitis." (PMID 39991157, 2025). "When bovine mastitis occurs, decreased KEAP1 and increased Nrf2, HO1, NQO1, and reactive oxygen species (ROS) indicate increased oxidative stress." (PMID 38630770, 2024). "Consistent with in vitro results, increased miR-223 also reduced Keap1 protein in experimental mastitis, based on both WB and IHC of experimental mastitis." (PMID 37710276, 2023). "Then, our objective was to emphasize the role of miR-223 in regulation of the NLRP3 inflammasome and Keap1/Nrf2 oxidative stress pathway in mastitis models involving LPS treatment of bMECs and murine mammary glands." (PMID 37710276, 2023). "The Keap1/Nrf2 system acts as a key regulator for protecting against ROS, with a crucial role in antioxidant metabolism and response, as well as in prevention of mastitis." (PMID 37710276, 2023). "Therefore, our objective was to determine the role of miR-223 in regulation of the NLRP3 inflammasome and Keap1/Nrf2 oxidative stress pathway in mastitis models involving LPS treatment of immortalized bovine mammary epithelial cells (bMECs) and murine mammary glands." (PMID 37710276, 2023). "Therefore, our results emphasized miR-223 may be a novel Keap1-targeting miRNA and further activated the Nrf2 cascade in an experimental mastitis model." (PMID 37710276, 2023). "Levels of IFN-γ, IL-4, TNF-α, MYD88, CCL5, TLR4, TLR9, LTF, PRLR, Keap1 and OXSR1 genes expression were significantly up-regulated in ewes affected with mastitis than resistant ones." (PMID 40542007, 2025). "Although miR-223 mitigated inflammation and prevented collateral damage during infection and inflammation, its function and regulation in response to NLRP3 or Keap1 treatment in bovine mastitis have not been well characterized." (PMID 37710276, 2023). "In the current investigation, qRT-PCR was used to measure the levels of antioxidant (CAT, GPX1, Keap1, OXSR1, ATOX1, GST, and Nrf2) and immune (IFN-γ, IL-4, TNF-α, MYD88, CCL5, TLR4, TLR9, LTF, and PRLR) genes in Barki ewes that were resistant and non-resistant to mastitis." (PMID 40542007, 2025).
multinodular goiter (5 papers, 2013 to 2025). Nodular goiter characterized by more than one discrete tissue mass. "To assess the prevalence of these mutations in pediatric tumors, we sequenced samples from the CHOP Biorepository (n = 191) using the CSTP and identified five papillary carcinomas and one benign multinodular goiter harboring KEAP1 mutations." (PMID 41573641, 2025). "The presence of these mutations is consistent with prior reports implicating KEAP1 germline variants in familial multinodular goiter." (PMID 41573641, 2025). "Collectively, our findings indicate that a germline heterozygous mutation of KEAP1 is associated with the development of multinodular goiter as one pathogenesis." (PMID 39373520, 2025). "Two independent case reports have described patients with hereditary multinodular goiters who harbored respective germline loss-of function mutations of KEAP1, leading to increased Nrf2 activation." (PMID 31428048, 2019). "The nuclear accumulation of NRF2, a protein associated with KEAP1, was shown at much higher rates in the patient’s nodules compared with nodules obtained from four unrelated patients with multinodular goiters." (PMID 27703446, 2016). "A germline mutation of KEAP1 gene was reported as a novel genetic abnormality associated with familial multinodular goiter." (PMID 27703446, 2016). "We report a hyperthyroid patient harboring a novel germline mutation (R483H) in KEAP1 gene who presented with a large multinodular goiter and Graves’ disease." (PMID 27703446, 2016). "A germline mutation of Kelch-like ECH-associated protein 1 (KEAP1) gene was reported as a novel molecular cause of familial multinodular goiter." (PMID 27703446, 2016). "All patients with multinodular goiter harbored KEAP1 mutations." (PMID 39373520, 2025). "However, germ-line KEAP1 mutations have been identified in a family with multinodular goiter, alluding to the importance of this gene to normal thyroid physiology." (PMID 24138990, 2013). "In rare cases of familial non-toxic multinodular goiter, KEAP1 mutations have been identified and linked to increased NRF2 accumulation and transcriptional activity." (PMID 41573641, 2025). "In the patient with multinodular goiter who did not harbor a KEAP1 mutation, TG expression in the nodule was equivalent to that in the nonnodular parenchyma, while NQO1 and GPX2 expression was very low in both regions." (PMID 39373520, 2025). "Genetic abnormality in KEAP1 is a rare disease and presents with familial multinodular goiter." (PMID 39373520, 2025). "A novel germline mutation (R483H) of KEAP1 gene was associated with the development of a non-toxic multinodular goiter." (PMID 27703446, 2016). "Collectively, our findings indicated that a novel germline mutation (R483H) of KEAP1 gene is associated with the development of a non-toxic multinodular goiter as one pathogenesis." (PMID 27703446, 2016). "However, germline mutations in KEAP1 have not been reported in cases of familial cancer; it has been detected in only 2 families with multinodular goiter." (PMID 39373520, 2025). "However, a germline mutation in KEAP1 has not yet been reported in familial cancer cases; it was detected only in a family with multinodular goiter." (PMID 27703446, 2016). "A total of 12 family members underwent genetic testing of the KEAP1 gene, including 9 patients with multinodular goiter and 3 family members without multinodular goiter." (PMID 39373520, 2025). "Indeed, several genetic abnormalities, including DICER1, KEAP1, and DGCR8, have been identified in familial multinodular goiter." (PMID 39373520, 2025).
pancreatic ductal adenocarcinoma (5 papers, 2011 to 2024). An infiltrating adenocarcinoma that arises from the epithelial cells of the pancreas. "The expression of Nrf2 and Keap1 was also analysed in pancreatic ductal adenocarcinomas (n = 66 and 57, respectively) and matching normal benign epithelium (n = 21 cases)." (PMID 21489257, 2011). "For instance, Kelch-like ECH-associated protein 1 (KEAP1) was absent in pancreatic ductal adenocarcinoma (PDAC) and negatively correlated with the malignancy of PDAC." (PMID 35996525, 2022).
pancreatitis (5 papers, 2020 to 2025). Inflammation of the pancreas. "Previous studies have shown that ROS-induced damage in pancreatitis can be mitigated through activation of the Keap1/Nrf2 signaling pathway." (PMID 40384872, 2025). "Kelch-like ECH-associating protein 1/nuclear factor erythroid 2-related factor 2-antioxidant response element (Keap1/Nrf2) signaling is a crucial element of antioxidative defense of cell, and alterations in this pathway are involved in the pathogenesis of pancreatitis." (PMID 36843131, 2023).
renal carcinoma (5 papers, 2017 to 2024). A carcinoma arising from the epithelium of the renal parenchyma or the renal pelvis. "In patients with solid tumors, nuclear accumulation of Nrf2 and low KEAP1 expression are linked to poor outcomes, though this has been underexplored in renal cancer." (PMID 39769005, 2024). "A growing amount of evidence suggest that an increased activity of Nrf2 due to NFE2L2 or KEAP1 mutations may play a pivotal role in the pathogenesis of many solid tumors and recently emerged as one of the main pathways implicated in Renal Carcinoma." (PMID 28061437, 2017). "Here also, we observed that the induction of c-Met markedly decreases the sorafenib-induced complex formation between Keap1 and Nrf2 in renal cancer cells." (PMID 30647407, 2019). "Of note, deregulation of Keap1/Nrf2 pathway was highlighted in the Papillary Type 2 subtype of renal cancer as a consequence of an abnormal fumarate accumulation in congenital fumarate hydratase deficiency which predisposes to PRCC2." (PMID 28061437, 2017). "Post-translational modifications of KEAP1 have an important role in renal cancer progression." (PMID 39769005, 2024). "This could be explained taking into account the heterogeneity features of renal cancer and more importantly by an existing alternative epigenetic mechanism to regulate Keap1-Nrf2 signalling." (PMID 28061437, 2017). "Fumarate hydratase inactivation results in fumarate accumulation, succination of the KEAP1 cysteine residues, and NRF2 activation in renal carcinomas." (PMID 31267557, 2019). "Moreover, our findings of KEAP1 hypermethylation provide the first indication that this epigenetic mechanism is important also in the regulation of KEAP1 expression in an aggressive renal cancer histotype and could represents an additional and attractive diagnostic and prognostic biomarker." (PMID 28061437, 2017). "Since no data are available regarding the contribution of KEAP1 hypermethylation in renal cancer, we decided to investigate this epigenetic mechanism of silencing by performing a comprehensive genetic and epigenetic analysis in 89 surgical resected RCCs." (PMID 28061437, 2017).
rheumatoid arthritis (5 papers, 2015 to 2024). A chronic, systemic autoimmune disorder characterized by inflammation in the synovial membranes and articular surfaces. "In rheumatoid arthritis synovial fibroblasts, calycosin significantly potentiated Nrf2 translocation by inducing p62 accumulation and Keap1 degradation to activate HO-1 and NQO1, thus suppressing IL-6 and IL-33 secretion and COX-2 mRNA and protein expression." (PMID 36358507, 2022).
schizophrenia (5 papers, 2015 to 2025). A major psychotic disorder characterized by abnormalities in the perception or expression of reality. "Fourth, a genetic analysis showed an epistatic interaction between NRF2 and KEAP1 gene variants on working memory in schizophrenia." (PMID 26107664, 2015). "Since evidence exists of a biological interaction between the NRF2 and KEAP1 proteins, the combined effect of NRF2 and KEAP1 genetic variants might influence the impairments in intellectual functions observed in schizophrenia." (PMID 26107664, 2015). "Cortical interneurons (cINs) were generated from human‐induced pluripotent stem cells (hiPSCs) of patients with schizophrenia and used to explore KEAP1 alterations during neurodevelopment." (PMID 40021790, 2025). "Patients with schizophrenia exhibited underexpression of KEAP1, a key regulator of ferroptosis, along with elevated intracellular Fe2+ levels and increased MDA concentrations, indicating enhanced lipid peroxidation and oxidative stress." (PMID 40021790, 2025). "In the present study, we observed an epistatic effect of the NRF2 gene and the KEAP1 gene on the impairment of working memory and processing speed in patients with schizophrenia." (PMID 26107664, 2015). "Analysis of NRF2 and KEAP1 genes was conducted with 183 patients with schizophrenia and 385 healthy subjects." (PMID 26107664, 2015). "In this study, we selected possible functional variants: rs10930781 in the NRF2 gene, and rs1048290 or rs11545829 in the KEAP1 gene in patients with schizophrenia and healthy controls." (PMID 26107664, 2015). "Besides, expressions of Nrf2 and Keap1 proteins in the parietal cortex from brain samples of schizophrenia patients were lower than those of healthy individuals." (PMID 33552387, 2021). "Finally, we examined the association between the KEAP1 and NRF2 genes and cognitive function in patients with schizophrenia." (PMID 26107664, 2015). "The Keap1 inhibitor sulforaphane increased blood and brain GSH levels in healthy humans and improved cognitive impairments in schizophrenia individuals." (PMID 33552387, 2021). "Another Keap1 inhibitor, curcumin, reduced total PANSS and the negative symptom subscale scores in schizophrenia." (PMID 33552387, 2021).
skin sensitization (5 papers, 2022 to 2025). An immunological response to previous exposure to a substance which results in an inflammatory skin reaction. "The nuclear factor erythroid 2 (Nrf2)–Kelch-like ECH-associated protein 1 (Keap1) pathway plays a vital role in skin sensitization." (PMID 38133374, 2023). "In contrast, KEAP1-sensing of epidermal damage can augment innate immune responses and facilitate skin sensitization as a result of increased expression levels of DAMPs, such as IL-1α." (PMID 35883888, 2022). "The Keap1–Nrf2–ARE pathway, a key cellular defence mechanism against electrophilic compounds and oxidative stress (known triggers of skin sensitization), regulates the expression of genes involved in antioxidant defence and detoxification." (PMID 40088110, 2025). "In conclusion, this study demonstrates the potential health risk posed by PAHs, particularly those found in children's toys, through their ability to activate the Keap1‐Nrf2‐ARE pathway, a key event in skin sensitization." (PMID 40088110, 2025). "Conversely, KEAP1-sensing of epidermal damage can lead to the activation of NRF2-mediated tissue-protective responses and exacerbate AD-like and psoriatic skin inflammation by inducing skin sensitization or KCs proliferation." (PMID 35883888, 2022).